SELENOT (selenoprotein T)
Description:
Selenoprotein with thioredoxin reductase-like oxidoreductase activity (By similarity). Protects dopaminergic neurons against oxidative stress and cell death. Involved in ADCYAP1/PACAP-induced calcium mobilization and neuroendocrine secretion (By similarity). Plays a role in fibroblast anchorage and redox regulation (By similarity). In gastric smooth muscle, modulates the contraction processes through the regulation of calcium release and MYLK activation (By similarity). In pancreatic islets, involved in the control of glucose homeostasis, contributes to prolonged ADCYAP1/PACAP-induced insulin secretion (By similarity).
Synonyms: SelT
Tractability: Antibody: UniProt predicts a signal peptide or a membrane-spanning region. PROTAC: ubiquitination databases record sites on it.
Gene: Protein-coding gene on chromosome 3 (150,602,875 to 150,630,436, forward strand). Ensembl gene ENSG00000198843.
Subcellular location: Endoplasmic reticulum membrane
Gene Ontology:
Molecular function: selenium binding; thioredoxin-disulfide reductase (NADPH) activity
Biological process: cell redox homeostasis; cellular oxidant detoxification; glucose homeostasis; insulin secretion involved in cellular response to glucose stimulus; pancreas development; positive regulation of cytosolic calcium ion concentration; positive regulation of growth hormone secretion; response to glucose; selenocysteine incorporation
Cellular component: endoplasmic reticulum; endoplasmic reticulum membrane
Genetic constraint (gnomAD): Loss-of-function variants: 5 observed, 11.1 expected, observed/expected ratio (o/e) 0.45, 90% interval 0.23 to 0.95. The upper end of that interval is the gene's LOEUF score, 0.95, which puts it in group 4 of 6, group 1 being the genes least tolerant of losing a copy. Missense variants: 97 observed, 136.1 expected, observed/expected ratio (o/e) 0.71, 90% interval 0.6 to 0.84. Synonymous variants: 56 observed, 53.88 expected, observed/expected ratio (o/e) 1.04, 90% interval 0.84 to 1.3.
Homologues: Orthologues: macaque SELENOT (99% identical), mouse Selenot (99% identical), rat Selenot (99% identical), rabbit SELENOT (98% identical), pig SELENOT (97% identical), dog SELENOT (97% identical), chimpanzee SELENOT (96% identical), guinea pig Selenot (94% identical), tropical clawed frog selenot (87% identical), zebrafish selenot1a (74% identical), zebrafish selenot1b (73% identical), Drosophila melanogaster SelT (36% identical), and 2 more.
Diseases named in the same sentence as SELENOT in open-access papers:
SELENOT is named in the same sentence as 21 diseases in open-access papers, as found by Europe PMC text mining. Sharing a sentence is not in itself a finding about the gene and the disease. The quoted sentences say what the papers report.
Parkinson disease (3 papers, 2018 to 2023). A progressive degenerative disorder of the central nervous system characterized by loss of dopamine producing neurons in the substantia nigra and the presence of Lewy bodies in the substantia nigra and locus coeruleus. "Among the mapped genes, the SELENOT gene is highly expressed in the cerebral globus pallidus and caudate nucleus in patients with Parkinson’s disease." (PMID 37550674, 2023). "Selenoprotein T participates in neuron protection against oxidative stress and in the prevention of onset and intensive movement impairment in Parkinson Disease animal models." (PMID 29758013, 2018).
selenium deficiency (2 papers, 2020 to 2025). A nutritional deficiency disease resulting from inadequate selenium levels in the body, which can lead to impaired function of selenoproteins essential for antioxidant defense and thyroid hormone metabolism. "Interestingly, several genes encoding selenoproteins (GPX1, GPX4, SELENON, SELENOM, SELENOF, SELENOW, SELENOT) were also downregulated, suggesting molecular evidence of selenium deficiency." (PMID 40459789, 2025).
breast carcinoma (1 paper, 2021). "We aimed to observe the effect of hsa-miR-33-5p on the apoptosis of breast cancer cells and to explore its regulatory relationship with selenoprotein T (SelT)." (PMID 33987194, 2021).
cardiac hypertrophy (1 paper, 2022). "miR-200a-5p inhibits the stress-associated selenoproteins (Sel), including selenoprotein 15 (Sep15), selenoprotein t (Selt), and selenoprotein p1 (Sepp1), impairs the Sel-mediated glucose metabolism, increases the glucose uptake in cardiomyocytes and leads to cardiac hypertrophy." (PMID 36613495, 2022).
diabetes (1 paper, 2021). "In addition, given that the role of SELENOT in diabetes seems to be somewhat similar to that of SELENOP, whether and how SELENOT and SELENOP interact with each other is an interesting topic." (PMID 34445217, 2021).
glioblastoma (1 paper, 2022). The most malignant astrocytic tumor (WHO grade IV). "In this work, we present for the first time the effects of the suppression of the activity of poorly studied selenoproteins SELENOM and SELENOT in human glioblastoma cells, which is extremely important for understanding the functions of these proteins in brain cells." (PMID 35741332, 2022). "In this work, for the first time, we studied changes in the redox status, calcium homeostasis, and expression of a number of key pro-apoptotic genes and ER stress regulators under conditions of reduced activity of two selenoproteins SELENOM and SELENOT in human glioblastoma cells (A-172)." (PMID 35741332, 2022). "We have shown that a decrease in the expression of SELENOM and SELENOT mRNA in the A-172 human glioblastoma cell line by more than 10 times and the quantitative content of enzymes by more than 3 times leads to ER stress, expressed as a decrease in the ER capacity for storing Ca2+ ions." (PMID 35741332, 2022). "Thus, despite the fact that both selenoproteins SELENOT and SELENOM belong to the same family of membrane proteins with thioredoxin-like folding and are localized in the ER, they have opposite effects on the expression of a number of pro-apoptotic genes in glioblastoma cells." (PMID 35741332, 2022).
Impaired glucose tolerance (1 paper, 2021). An abnormal resistance to glucose, i.e., a reduction in the ability to maintain glucose levels in the blood stream within normal limits following oral or intravenous administration of glucose. "Intriguingly, male conditional pancreatic β-cell Selenot-KO mice displayed impaired glucose tolerance and a deficit in insulin production/secretion, suggesting that SELENOT is involved in glucose metabolism by disrupting insulin production/secretion." (PMID 34445217, 2021).
lymphoma (1 paper, 2022). A malignant (clonal) proliferation of B- lymphocytes or T- lymphocytes which involves the lymph nodes, bone marrow and/or extranodal sites. "Finally, when comparing these donor-derived CD4 T-cells with lymphoma-derived cell lines, common features emerged, most notably the high expression of GPX4, TXNRD1 and SELENOT transcripts." (PMID 35163318, 2022).
pituitary cancer (1 paper, 2022). A primary or metastatic malignant neoplasm affecting the pituitary gland. "Thus, it was shown that in mouse pituitary cancer cells (AtT20 cell line), a decrease in SELENOT activity, on the contrary, contributed to an increase in oxidative and ER stress, which led to a decrease in the viability of these cells." (PMID 35741332, 2022).
prostate carcinoma (1 paper, 2021). A carcinoma that arises from epithelial cells of the prostate gland. "In prostate carcinoma cells, SeNP did not significantly affect the expression of the seven studied selenoproteins; a twofold increase in the expression of SELENOT, SELENOK, SELENON, and DIO2 can be noted." (PMID 34360564, 2021).
steatosis (1 paper, 2021). Increased lipid within the cytoplasm of cells. "Amongst the 13 genes, eight (DIO1, GPX2, SEPHS2, SELENOK, SELENOS, SELENOT, SELENOF, and SELENOW) had higher, and five (DIO3, GPX1, SELENON, SELENOO, and TXNRD3) had lower expression in steatosis." (PMID 34869521, 2021).
sterility (1 paper, 2021). "Based on our findings, it is possible that deletion of SELENOT may affect spermatogenesis and, thus, cause sterility in mice." (PMID 34445217, 2021).
cancer (4 papers, 2019 to 2022). A tumor composed of atypical neoplastic, often pleomorphic cells that invade other tissues. "Overall, the KEGG analysis of DEPs has provided new directions for research into the role of SELENOT in human diseases and organismal systems, including but not limited to the role of SELENOT in lipid metabolism-related diseases, cancer and complement system deficiency diseases." (PMID 34445217, 2021). "Previously, we and other authors have shown that methylselenic acid (MSA), sodium selenite (SS), and selenium nanoparticles (SeNP) can affect the expression of SELENOM and SELENOT mRNA in various cancer and normal cells, depending on the concentration and time of exposure." (PMID 35741332, 2022). "Notably several of these genes are ER-resident selenoproteins (SELENOF, SELENOM, SELENON, SELENOT), thought to be involved in ER-stress response and calcium flux, comprising a potentially important mechanism of selenoprotein-related cancer prevention or promotion." (PMID 31027226, 2019). "Another possible explanation for the lack of influence of SELENOM-KD on the proliferative properties of cancer cells is the increased expression of SELENOK and SELENOT, two other selenoproteins localized in the ER." (PMID 35741332, 2022).
heart disease (1 paper, 2024). "Although the mechanisms behind this response remain a matter of analysis, these findings may further delineate SELENOT as a potential sensor protein in stressed cardiomyocytes and provide first evidence on its potential biomarker role in the hypertrophic heart/heart disease." (PMID 38643121, 2024).
SELENOT also shares sentences with these, for which no sentence is quoted: bladder cancer (1 paper); cardiovascular disease (1); endotoxemia (1); fibrosarcoma (1); gastric cancer (1); heart failure (1); tumor (1).